CD163 (CD163 molecule)
Diseases named in the same sentence as CD163 in open-access papers (continued):
Sharing a sentence is not in itself a finding about the gene and the disease.
glioblastoma (42 papers, 2016 to 2026). The most malignant astrocytic tumor (WHO grade IV). "Our analysis suggests a closer association of Iba1+ macrophages with GSCs than between CD163+ macrophages and GSCs in glioblastoma." (PMID 40136662, 2025). "The results of this multimodal mapping fit well with our histopathological observations on a divergent and variable association of IBA1 positive microglia/macrophages and CD163 immunoreactive cells and with necrosis in glioblastoma." (PMID 40191733, 2025). "One striking finding of this study is that IBA1 and CD163 labeling, and by inference microglial cells and bone marrow-derived brain macrophages, exhibit a divergent and variable association with necrosis in glioblastoma." (PMID 40191733, 2025). "Meanwhile, CD163 was also associated with immune infiltration in glioblastoma multiforme." (PMID 35387222, 2022). "A recent study reported an association between CD70 expression and infiltration of CD163+ (a marker of M2 macrophages) tumor-associated macrophages (TAMs) in glioblastoma, suggesting a (in)direct role for CD70 in recruitment and/or activation of tumor promoting TAMs." (PMID 34991665, 2022). "IHC validation demonstrated increased expression of the M1 markers iNOS, IL-1β, as well as the M2 marker CD163, in SAMD9high glioblastoma tissues relative to SAMD9low tissues." (PMID 41331572, 2025). "Using this powerful new technology, we have specifically studied the tissue distribution of Iba1+ and CD163-expressing macrophages in human glioblastoma biopsies in relation to CD276+ GSCs, with the aim of gaining insights into their in situ relationship." (PMID 40136662, 2025). "This highlights significant intra-tumoral heterogeneity of Iba1 and CD163 expression among glioblastoma biopsies, in keeping with a recent study on glioblastoma necroses." (PMID 40136662, 2025). "IBA1 and CD163 showed remarkable differences in our study in relation to glioblastoma tumor necrosis." (PMID 40191733, 2025). "Specifically, Iba1-immunoreactive microglia are more commonly found in viable tumor areas, whereas CD163-expressing macrophages, likely of recent bone marrow origin, predominate in necrobiotic and necrotic tissue areas of glioblastoma." (PMID 40361384, 2025). "The following considerations assist in evaluating the complex tissue expression of Iba1 and CD163 in glioblastoma." (PMID 40361384, 2025). "CD11b+/CD163+ macrophages can stimulate the growth and survival of glioblastoma cells through PTN-PTPRZ1 signaling." (PMID 40191211, 2025). "The two microglia/macrophage markers employed in this study, IBA1 and CD163, showed strikingly different patterns of expression between glioblastoma cases." (PMID 40191733, 2025). "Our DSP results focused on CD163+ rich regions within tumor to approximate immune signatures of immunosuppressive myeloid cells in glioblastoma." (PMID 39346903, 2024). "Upon desialylation of the glioblastoma cells, this induction of CD163 was hampered, and furthermore, the monocytes were now able to secrete higher amounts of IL-6 and TNFα compared to fully sialylated glioblastoma cells." (PMID 39065651, 2024). "Pericytes and macrophages recognized by MCAM/CD163 gene pair expression have been identified as a potential prognostic immune signature co-expressed in glioblastoma (GBM) samples." (PMID 39086395, 2024). "Iba1-, CD32a- and CD163-expressing TAMs were abundant in the glioblastoma cores (protein load 6.11, 7.41 and 3.09%, respectively)." (PMID 37324244, 2023). "Programmed death-ligand 1 expression was associated with microglia/macrophage markers (including anti-inflammatory) CD68, CD163, CD32a and triggering receptor expressed on myeloid cells 2, only in the leading edge of glioblastomas (P < 0.01)." (PMID 37324244, 2023). "We also observed a robust number of intratumoral microglia highlighted by CD68 and CD163 immunostaining in de novo RRD glioblastomas." (PMID 38079020, 2023).
glioblastoma (continued). "Steroids are known to significantly influence immune cell function and phenotype and alter the expression of PSGL-1, CD163, and HLA-DR on circulating monocytes of glioblastoma patients in the present study (Figure A2b)." (PMID 36497232, 2022). "Here, they also showed that the presence of CD70 on tumor cells and CD163 on TAMs correlated with poor prognosis for glioblastoma patients." (PMID 34991665, 2022). "IGFBP2 induced immunosuppression by decreasing CD8+ T and CD19+ B cells and increasing CD163+ M2 TAMs; blocking this gene suppressed tumor growth and improved survival in a glioblastoma mouse model." (PMID 33790966, 2021). "IBA1 and CD163 showed remarkable differences in relation to glioblastoma tumor necrosis." (PMID 40191733, 2025). "We investigated the regulation of two well-established markers for microglia and brain macrophages, IBA1 and CD163, in relation to glioblastoma tumor necrosis using immunohistochemistry and modality fusion heatmaps of whole slide images obtained from adjacent tissue sections." (PMID 40191733, 2025). "Compared to normal brain tissues, glioblastoma tissues contained more CD163/CD206 positive cells." (PMID 39431006, 2024). "As such, a higher level of CD163 in dendritic cell cultures of glioblastoma patients may reflect an inflammatory property." (PMID 38534379, 2024). "Co-culturing monocytes with glioblastoma cells induced CD163 expression on the monocytes." (PMID 39065651, 2024). "Due to the heterogeneity of glioblastoma and the difficultly of distinguishing all malignant cells in areas with a high content of macrophages without additional markers, regions of the tumors were selected with minimal CD163 infiltration." (PMID 29888503, 2018). "Similarly, more CD163+/CD206+ cells were detected in IDH-WT than in IDH-mutant glioblastomas." (PMID 39431006, 2024). "The transwell assay indicated that glioblastoma cells co-cultured with M2 (CD11b+/CD163+)-derived conditional medium in which EVs were excluded or inhibited by GW4689 showed decreased migration and invasion ability, and the decrease could be restrained by M2 (CD11b+/CD163+) derived EVs." (PMID 39431006, 2024). "In an independent large glioblastoma cohort with transcriptomic data, positive correlations between anti-inflammatory microglia/macrophage markers (triggering receptor expressed on myeloid cells 2, CD163 and CD32a) and CD4+/CD8+/programmed death-ligand 1 RNA expression were validated (P < 0.001)." (PMID 37324244, 2023). "It was discovered through this platform that in comparison with proneural GBM, glioblastomas affecting the mesenchymal niche attracted significantly higher levels of CD163+ M2 TAMs and PD‐1/PD‐L1 and responded better to ICI treatment." (PMID 35782339, 2022). "LDA analysis revealed multiple distinct recurrent cellular neighborhoods in adult glioblastoma, including a neighborhood that combined CD39, CD73, SOX2, and CD163 expressing cells (Topic #11)." (PMID 35973991, 2022). "Treatment of mouse glioblastoma microglia with both recombinant and glioma-released CXCL16 increased the expression of anti-inflammatory genes ARG1, CHIL3, RETNLA and CD163 that was impaired by anti-CXCL16 antibodies." (PMID 36686729, 2022). "We investigated paired human glioblastoma samples from primary and subsequent progressive disease for the presence of CSF1R, CD204, CD163, PD1, PD-L1, CD3, CD4, and CD8." (PMID 34063518, 2021).
glioblastoma (continued). "It is conceivable that in the necroses of glioblastoma, ADAM17-mediated shedding of membrane CD163 from macrophages occurs which could explain the presence of the large amounts of extracellular CD163 we observed in necrotic tissue areas in this study." (PMID 40191733, 2025). "A new population of immunosuppressive microglia, CD163+HMOX1+, was also identified, exhibiting anti-T cell activity through the secretion of IL-10, and this population is found to be limited in mesenchymal glioblastomas." (PMID 40191211, 2025). "Tissue sections from resected low-grade, meningioma, and glioblastoma (grade IV) tumors and epilepsy tissues were immunofluorescently triple-labeled for Iba1 (pan-myeloid marker), CD14 or CD163 (preferential TAM markers), and either P2RY12 or TMEM119 (microglial-specific markers)." (PMID 34286275, 2021). "Furthermore, the histological picture of IBA1 and CD163 immunostains in glioblastoma is complex also in non-necrotic areas." (PMID 40191733, 2025). "Intact appearing CD163 expressing macrophages which may be recently blood-derived could be one source of the large amounts of CD163 which is deposited in many but not all areas of glioblastoma necrosis." (PMID 40191733, 2025). "However, we have observed striking differences in the regulation of the microglia and brain macrophage markers, IBA1 and CD163, in relation to glioblastoma tumor necrosis, and in the distribution of non-cell bound macrophage antigen in the case of CD163." (PMID 40191733, 2025). "EVs from patients suffering from glioblastoma (GBM) are capable to polarize CD14+ and CD163+ monocytes toward the M2 anti-inflammatory phenotype, enhancing blood serum concentrations of colony-stimulating factor 2 and 3, as well as to detect interleukin-2, -4, and -13." (PMID 37511010, 2023). "Collectively, these data suggest that in the context of glioblastoma, CD14 and CD163 are not strictly TAM-specific markers and can be expressed by both myeloid cell populations, likely dependent on activation state." (PMID 34286275, 2021). "CD335 was positively associated with PD-L1 at both the leading edge and infiltrating zone of glioblastomas (P < 0.01) but not in the core; CD335 also positively correlated with CD8+ T cells as well as with CD68/CD163/TREM2 TAMs only at the leading edge (P < 0.01)." (PMID 37324244, 2023).
lymph node metastasis (38 papers, 2014 to 2026). "Our univariate analysis found that in CRC patients, lower differentiation, advanced TNM stage, and lymph node metastasis were associated with higher expression of CD163+ TAM and lower expression of CD86+ TAM." (PMID 41395618, 2025). "A high density of CD163+ M2 macrophage infiltration was significantly associated with lymph node metastasis (P = 0.006)." (PMID 35280439, 2022). "High CD163 expression was associated with invasion depth (p = 0.037), lymph node metastasis (p = 0.021), distant metastasis (p = 0.007) and TNM stage of patients (p = 0.003)." (PMID 34655278, 2021). "At the same time, CD163+ M2 TAM density was associated with lymph node metastasis (OR = 2.42, 95% CI: 1.09–5.37; WMD = 39.37, 95% CI: 28.25–50.49) and FIGO stage (WMD = -33.60, 95% CI: -45.04 to -22.16)." (PMID 33928349, 2021). "As for CD163+ M2 TAMs, high stromal CD163+ TAM density was associated with lymph node metastasis [OR = 2.42, 95% CI: (1.09, 5.37), P=0.03; I2 = 0%, P=0.52]; [WMD = 39.37, 95% CI: (28.25, 50.49), P<0.001; I2 = 0%, P=0.99]." (PMID 33928349, 2021). "The expression levels of CD68 in tumor cells were only associated with lymph node metastasis (P = 0.044), while the expression of CD163 was significantly associated with the recurrence (P = 0.013) and mortality (P = 0.001)." (PMID 26769084, 2016). "In bladder cancer, PET/CT also demonstrates high sensitivity and specificity in evaluating lymph node metastasis, particularly in the mediastinal and abdominal lymph node regions, where higher metabolic activity is closely associated with CD163+ M2 macrophage infiltration levels." (PMID 41575920, 2026). "We could however show, that CD169+ macrophages in association with lymph node metastasis expressed CD163." (PMID 37404831, 2023). "Similarly, high levels of tumour stroma CD163+ TAMs were associated with lymph node metastasis in OSCC." (PMID 37397243, 2023). "Both CD68+ and stromal CD163+ M2 TAM density were associated with lymph node metastasis in CC." (PMID 33928349, 2021). "Because lymph node metastasis is the major cause for penile cancer-related deaths, we considered that CD163+ macrophages may have a clinical significance as a prognostic factor in patients with hrHPV+ PSCC." (PMID 34194435, 2021). "IHC analysis of Chinese cohort of 81 patients with CRC showed that high expression of stromal CD163 at tumor invasive front was significantly associated with tumor grade, lymphovascular invasion, tumor invasion, lymph node metastasis, and TNM stage and correlated with poor RFS." (PMID 33194645, 2020). "Previous studies have found that CD163 expression in cancer cells is positively correlated with macrophage infiltration and strong macrophage infiltration is associated with better cancer-specific survival, but macrophage infiltration is negatively correlated with lymph node metastasis." (PMID 41575920, 2026). "Furthermore, hrHPV+ patients with aggressive tumors, may benefit from such combinatorial therapy, as we showed a probable association between high infiltration rates of CD68+ and CD163+ cells in the peritumoral tumor (PT Tumor) and lymph node metastasis." (PMID 34194435, 2021). "In this study, we investigated the impact of macrophage infiltration, specifically CD163+ M2 macrophages, on the diagnostic accuracy of [18F]FDG PET imaging in identifying mediastinal and abdominal lymph node metastases in cancer patients." (PMID 41575920, 2026). "In conclusion, increased CD163+M2 macrophage infiltration correlates with higher SUVmax values and more frequent detection of lymph node metastases." (PMID 41575920, 2026). "There is also a significant correlation between CD163+ M2 macrophages and lymph node metastasis of colorectal cancer." (PMID 41575920, 2026).
lymph node metastasis (continued). "ITGβ8 expression in LUAD was positively correlated with lymph node metastasis classification (p = 0.000) and T classification (p = 0.009), while CD163 expression in LUAD was positively correlated with T classification (p = 0.003)." (PMID 39535362, 2025). "Others have also demonstrated a correlation between CD163-positive macrophages and higher T-stage, lymph node metastases, increased grade, elevated Ki-67 proliferation index, and HER2 positivity." (PMID 40510346, 2025). "The levels of CD163+ immune cells were determined in 117 PT, 70 lymph node metastases (LNM) and 59 distant metastases (DM)." (PMID 39751847, 2025). "Clinical studies reveal that both CD68+ M1 and CD163+ M2 TAMs correlate with lymph node metastasis, with CD163+ TAMs further predicting advanced FIGO stage and poor prognosis." (PMID 40808954, 2025). "The lymph node metastasis rate in the high-CD163 expression group (36.1%) was significantly higher than that in the low-CD163 expression group (21.5%) (p < 0.05)." (PMID 36900416, 2023). "The results of this study revealed that the density of CD163+ M2 macrophages was significantly higher in tissue samples from patients who had a poor prognosis (P < 0.05) or with lymph node metastasis (P < 0.05)." (PMID 35280439, 2022). "Our data showed a strong association between the number of TAMs and cN stage (p = 0.026), with higher numbers of CD163-positive TAMs in tumors with lymph node metastasis." (PMID 34733785, 2021). "And CD163+ M2 TAM infiltration was associated with more advanced FIGO stage and lymph node metastasis in CC." (PMID 33928349, 2021). "Next, in order to further characterize the M2 cell subsets present in lung tumors we compared the profile of CD163+/CD206+ cells isolated from chemoresistant patients with lung or lymph node metastasis with wild type (WT) or mutant (MT) Kras status." (PMID 34326381, 2021). "We focused on the association between CD163+ M2 TAM infiltration and clinicopathological parameters of cervical cancer, such as lymph node metastasis, histological grade as well as FIGO stage." (PMID 33928349, 2021). "Previous studies revealed that CD163+ macrophages were positively correlated with lymph node metastasis, hormone receptor negativity, and Ki67 positivity." (PMID 33178603, 2020). "Meanwhile, the expression of CD163 macrophages is positively related to the distant lymph node metastasis." (PMID 32332633, 2020). "CD163+ macrophages were also predictive of the lower tumor grade and less lymph node metastasis that was demonstrated by next-generation tissue microarray construction." (PMID 33194645, 2020). "We found that CD68 and CD163 double-positive macrophages were more likely to be distributed in tumors with lymph node metastasis (P < 0.001) and had high histological grade (P < 0.001) and Ki67 index (P < 0.001) as well as negative HR expression (P < 0.001)." (PMID 31528210, 2019). "CD163-, CD204-, and CD206-positive macrophages are significantly associated with poor prognosis, pTNM staging and lymph node metastasis in lung cancer, and thus CD163, CD204, and CD206 are considered as useful markers for activation of TAMs." (PMID 31601953, 2019). "In addition, the infiltration of M2-polarized (CD163 +) TAMs was positively correlated with T stage (P = 0.006), lymph node metastasis (P = 0.014), and clinical stage (P < 0.001)." (PMID 39073672, 2024). "In the LSCC samples with lymph node metastasis, the mean density of CD163+ M2 macrophage infiltration was 124.2 ± 52.7 per 200 fields, whereas in the LSCC samples without lymph node metastasis, the mean density of CD163+ M2 macrophage infiltration was 103.3 ± 28.1 per 200 fields." (PMID 35280439, 2022). "Furthermore, the relationships between M2 macrophages identified by expression of CD163 and lymph node metastasis were analyzed using the independent sample t-test and Chi-square test." (PMID 33781288, 2021).